FOXP3 (forkhead box P3)
Diseases named in the same sentence as FOXP3 in open-access papers (continued):
Sharing a sentence is not in itself a finding about the gene and the disease.
tumor (continued). "In contrast, in IAs from less immune-infiltrated tumors, neighborhoods centered by CD3+ T cells contain higher numbers of CD20+ and CD4+FOXP3+ cells per each tumor cell and less HLA1+ tumor cells, favoring potential immunosuppressive environment." (PMID 31166985, 2019). "Accordingly, double immunofluorescence on paraffin embedded tumours revealed that CD4+ and FOXP3+ T cells (Treg) were positive for LY6G6D staining, whereas CD8+ T lymphocytes did not." (PMID 30670049, 2019). "Nevertheless, we found that HCC patients with a high potential neoepitope, coupled with a favorable tumor microenvironment, as assessed by high expression of GZMA, low expression of FoxP3 and PDL1, tended to have a prolonged survival." (PMID 31756926, 2019). "A recent study showed delayed tumor growth, decreased production of IL-10, IL-2, and TGF-β, and increased survival of mice after inoculation of the FOXP3-silenced B16F10 melanoma cell line compared to mice injected with the wild-type cell line." (PMID 31547627, 2019). "In the survival analysis, peripheral DC2s (P = .038), tumor‐infiltrating DC1/DC2 cell ratios (P = .012), Foxp3 + Tregs (P = .048), and IDO expression (P = .043) were significantly correlated with OS, at T (P < .01), N (P < .01), and TNM (P < .01) stages." (PMID 31631566, 2019). "Tregs, especially CD4+CD25+Foxp3+, are one of the most studied immune cells owing to their specific inhibitory influence on HCC tumour growth and progression." (PMID 30893948, 2019). "There was no statistical correlation between the expression of PD-L1 in the tumor cells or in TAM, CD8/FOXP3 ratio in the center or edge of the lesions, or CD8 edge/center ratio or FOXP3 edge/center ration and time to first relapse." (PMID 31640798, 2019). "We then calculated the ratio of pro-tumor immune cells (MDSCs, TAMs and Tregs) to anti-tumor immune cells (IFN-γ+ CD8+ and Foxp3− CD4+) as an indicator for the overall immune balance within the tumor microenvironment." (PMID 31015520, 2019). "A significant positive correlation between the intratumor FoxP3+ Tregs and the level of TGF-β1 was observed in tumor tissue of GC patients (R2 = 0.4192, P < 0.0001)." (PMID 31417548, 2019). "We used immunofluorescence to co-localize Treg (Foxp3) and cytotoxic T cells (CD8) in tissues from different stages of disease and found that Treg cells infiltrate early, persist throughout tumour development, and outnumber CD8+ T cells in each stage of ODI." (PMID 31439856, 2019). "We also assessed the number of HLA-1+ tumor cells, CD3+, CD20+, CD8+PD1 and CD4+FOXP3+ cells, per each tumor cell within the CD3+ cell neighborhoods within IAs." (PMID 31166985, 2019). "Compared to adjacent tumor-free colon, CD4+ FOXP3+ T cells and ST2-positive Tregs were more abundant in human CRC lesions, yet ST2 expression levels were unchanged in tumor tissue." (PMID 31165767, 2019). "Also, FOXP3 might mediate the inhibiting efficacy of tumor cells to escape immune attack." (PMID 31653148, 2019). "We showed that the proportion of CD4+CD25+ Tregs in lymphocytes increased significantly after co-culture, and Foxp3, NRP1 and CTLA-4 expression on the surface of the cells were upregulated, indicating that the tumor cells stimulated T cell immune responses." (PMID 31417646, 2019). "A high ratio of stromal FOXP3 to CD3+ cells, favors a pro-tumor environment and predicts cancer progression." (PMID 31827925, 2019). "EMT tumor cells also induced the generation of immunosuppressive regulatory DCs (DCreg), which induced immunosuppressive CD4+Foxp3+ Tregs and eventually impaired the induction of antitumor CTLs." (PMID 31096701, 2019). "Using immunohistochemistry, tumor tissues were stained with antibodies against CD3, CD8, CD163, iNOS, Forkhead box P3 (FOXP3), and CD33." (PMID 30729718, 2019).
tumor (continued). "On the other hand, suppressive Foxp3+ regulatory T (Treg) cells, which represent a significant proportion of the CD4+ population in tumors, have been shown to increase with tumor stage and correlate with poor prognosis in invasive carcinomas." (PMID 31555258, 2019). "The tumour samples were stained for inducible nitric oxide synthase (iNOS, M1 marker), CD163 (M2 marker), FoxP3 (Treg marker), CD47 and IDO1." (PMID 31358801, 2019). "The leucocytes in the mimic distant tumours were collected and co-stained with CD3, CD4 and Foxp3 for further analysis." (PMID 31048681, 2019). "The results showed that most commonly detected immune cells at the tumor site were CD8+ TILs, followed by CD4+ TILs; Foxp3+ regulatory T (Treg) cell were 12%." (PMID 31620360, 2019). "Flow cytometric analyses of TILs revealed that L-NAME combined with an anti-PD-1 blockade tended to decrease tumor-infiltrating CD4+FOXP3+ regulatory T cells, and significantly increased the CD8+/CD4+FOXP3+ ratio in MCA205WT tumors." (PMID 31481761, 2019). "All the cases were scored for FOXP3+ regulatory T-cells (Treg) and CD8+ cytotoxic tumor infiltrating lymphocytes (TIL) densities, as well as PD-L1 expression in tumor cells and tissue associated macrophages." (PMID 31640798, 2019). "Baseline sTILs and FOXP3+ Tregs and MPI in tumor tissues from BC patients in the pCR group were higher than those in the Non-pCR group (PsTILs = 0.035, PTregs = 0.027, PMPI = 0.005)." (PMID 32039020, 2019). "Further, preclinical studies have shown that FOXP3+ Tregs cells inactivation or depletion results in induce strong intratumoral invasion of CD8+ T cells and complete tumor eradication." (PMID 31337018, 2019). "Strong correlations were discovered among the densities of PD-L2 tumor cells, CD3+ T cells, CD8+ T cells, and FOXP3+ Tregs in the tumor and stroma (all P < 0.001)." (PMID 31464648, 2019). "Our findings from in vitro functional studies and from transcriptomic analyses of tumor tissues and CRC-isolated Tregs also indicate an implication of the IL-33/ST2 axis in the regulation of IL-17A expression by FOXP3+ Tregs and FOXP3− CD4+ T cells." (PMID 31165767, 2019). "Quantification of the T cells per square mm of tumor revealed that the stroma of VSCC was more densely infiltrated with CD3+ T cells, CD3+CD8−Foxp3− T cells, CD3+CD8−Foxp3+ Tregs, and CD3+CD8+Foxp3− T cells than healthy controls." (PMID 31481117, 2019). "Tumor-infiltrating T-cells were observed following 90Y-NM600 treatment with increased levels of CD8 + lymphocytes and a low abundance of regulatory Foxp3 + T-cells." (PMID 30820474, 2019). "Tissue sections from intracranial CT2A-dmEGFRvIII-Luc (A) and SMA560-dmEGFRvIII-Luc (B) tumors were analyzed for the expression of PD-1 and FoxP3 on CD4+ and CD8+ T cells and PD-L1 on tumor cells." (PMID 31142380, 2019). "The enhanced efficacy was associated with the increased CD8 + T cell, increased effector memory T cells (CD44 + CD8 + CD62L+), decreased Treg (CD4 + CD25 + Foxp3+) and M2 macrophages (F4/80 + CD206+) in the tumor microenvironment." (PMID 31882868, 2019). "Here, the authors show that specialized subsets of tumour-infiltrating dendritic cells induce distinct CD4+ T cell programs and specifically identify a CD103–CD11b+ subset which induces tumor-promoting FoxP3– Type-1 regulatory T cells." (PMID 30926808, 2019). "This was confirmed in the current set of 43 tumours, by determining the numbers of lymphocytes (CD3+, CD4+, CD8+, FoxP3+; using immunofluorescence (IF)) and macrophages (CD68+, CD163+, CD68+CD163+; using IF)." (PMID 31337000, 2019). "Responders were associated with higher CD8+ cells but lower CD4+ cells infiltration, lower Foxp3 + Treg density and higher CD8+ to Treg ratio (responder vs non-responder), indicating strongly enhanced T effector function within the tumours." (PMID 30587849, 2019).
tumor (continued). "Baseline tumor biopsies from a subset of patients were also analyzed for the presence of programmed cell death-ligand 1 (PD-L1), CD8, FoxP3, and 4-1BB/CD137." (PMID 31801624, 2019). "Foxp3 mRNA level was significantly increased in tumor tissues after laparotomy, whereas knockdown of CCL18 partially destroyed laparotomy‐induced upregulation of Foxp3." (PMID 30216450, 2019). "Meanwhile, ELISA assay confirmed that CCL18 protein level in the peritoneal cavity was increased, along with the relationship between the Foxp3 level and the CCL18 level in tumor tissues was shown." (PMID 30216450, 2019). "We provide here a study of the expression of PD-L1 and the density of FOXP3 Treg and CD8+ T-cells to better understand the role of tumor microenvironment in a well characterized cohort of pc-CD30-LPD from an academic medical center in Brazil." (PMID 31640798, 2019). "Intracranial CT2A-dmEGFRvIII-Luc (A-D) and SMA560-dmEGFRvIII-Luc (E-H) tumors were analyzed for the expression of PD-1 on CD4+ and CD8+ T cells, FoxP3 on CD4+CD25+ T cells and PD-L1 on tumor cells." (PMID 31142380, 2019). "In tumor-infiltrating Tregs, both STAT3 and STAT5 bind to a STAT consensus site in the Foxp3 promoter to enhance FOXP3 expression which seems to be important in maintaining Tregs inhibitory functions." (PMID 31480382, 2019). "In immunogenic tumors, SLR14 significantly increases the tumor infiltration of cytotoxic CD8+ T cells, NK cells, and CD11b+ myeloid cells while decreasing the immunosuppressive CD4+FoxP3+ T reg cells." (PMID 31601678, 2019). "At T, N, and TNM stages, the expression levels of peripheral DC2s, tumor‐infiltrating DC1/DC2 ratios, Foxp3 + Tregs, and IDO were significantly correlated with prognosis (P < .05)." (PMID 31631566, 2019). "Tumor-infiltrating CD4+ T cells showed the highest relative ratio of ST2-expressing cells and a substantial proportion of CD4+ T cells in CRC lesions were FOXP3+ Tregs." (PMID 31165767, 2019). "FoxP3 positivity localized in the nuclei of a subset of lymphocytes, and membranous CD47 positivity was seen in tumour cells of 78% of tested cases." (PMID 31358801, 2019). "Single IF slides were stained for PD-1, PD-L1, CD8, FoxP3, CD163, and a tumor marker (e.g. Sox10/S100 for melanoma) using primary antibodies at manufacturer’s recommended concentrations and visualized with an Opal kit (PerkinElmer)." (PMID 30400835, 2018). "Forkhead Box Protein P3 (FOXP3), a transcription factor of the FOX protein family, is essentially involved in the development of regulatory T (Treg) cells, and functions as a tumor suppressor." (PMID 30011797, 2018). "PD-1/PD-L1 signaling pathway has different effects on T cells, such as downregulation of effector T cell levels, induction of apoptosis of tumor-infiltrating T cells, and promoting CD4+ T cell differentiation into suppressive Foxp3+ Tregs." (PMID 29868037, 2018). "With ‘TF regulation’ checked, TF-TG correlation coefficients are provided and then user can get the TFs targeting CCNA1, CCNA2 and see that the correlation coefficient between FOXP3 and CCNA2 is much different in normal samples (0.58) and tumor samples (0.16)." (PMID 29504910, 2018). "We found a beneficial change in the immunologic balance within the tumor microenvironment after NACT, namely, decreased Foxp3+ T cells and stable CD8+ T cells." (PMID 30474571, 2018). "More specific flow-cytometric analysis confirmed 4- to 5-fold increases in the percentage of tumor-infiltrating CD8+ and CD4+ T cells, with concomitant reduction in the percentage of CD4+/FoxP3+ regulatory T cells (Tregs)." (PMID 29433938, 2018). "The role of TILs, T effector (CD8+, CD4+) and T regulatory (FOXP3+, CTLA-4+, PD-1+) cells and CD56+ NK cells in ALNs is even less well studied and their contribution to the induction of immune-mediated tumour cell death in ALN metastases poorly documented." (PMID 29390966, 2018).
tumor (continued). "We have characterised further the key contributions of tumour-infiltrating TILs, T effector (CD4+, CD8+), T regulatory (FOXP3+, CTLA-4+) and CD56+ NK cells to pCRs in ALN metastases." (PMID 29390966, 2018). "Our model utilizes four immune variables which are significantly associated with clinical outcomes for ESCC, including the infiltration of CD8+/Foxp3+/CD33+ cells and the expression of PD-L1 by tumor cells." (PMID 30285868, 2018). "Percentages of CD11c+ dendritic cells, B220+ B cells, CD4+ and CD8+ T cells, forkhead box protein (FoxP3+) regulatory T cells, and NK1.1+ natural killer (NK) cells were the same in spleens of MCA205 tumor-bearing WT and S100A4−/− mice." (PMID 29556233, 2018). "We also provided evidences indicating that overexpressed STAT5 combines with TET2 to form complexes that bind to the FOXP3-TSDR, resulting in excessive demethylation in tumor-infiltrating CD4+ T cells." (PMID 30013992, 2018). "In tumor, paired biopsies showed ≥ 2-fold increased expression of PD-L1 and/or CD8+ T cell infiltration in 7/14 patients, with a 60% median reduction in OX40+FOXP3+ cells at doses of 1 and 3 mg/kg compared with doses <1 mg/kg." (PMID 30400822, 2018). "Increased numbers of FoxP3+/CD25+ Tregs are observed in a subset of human OSCC and in the early stages of tumour progression in several mouse models." (PMID 30143634, 2018). "Regulatory T cells (Tregs), a subset of CD4 T cells characterized by FoxP3 and CD25 expression, suppress the anti-tumor immune response and restricts the expansion and differentiation of effector T cells." (PMID 29546043, 2018). "Immunocytochemical analysis revealed that Foxp3 and Stat3 protein expression in the abdominal ascites were significantly reduced in PRP-treated tumor-bearing mice compared to control mice." (PMID 29735884, 2018). "Finally, the Foxp3 promoter behaves as an integration site between canonical NF-κB and different signaling pathways that could cooperatively or antagonistically influence Tregs behavior in tumor microenvironments." (PMID 30364244, 2018). "The number of each cell-type and location in tumour nest or stroma was determined for total T cell (CD3), CD8 T cells (CD8), T-reg (FoxP3) and macrophages (CD68) and related to survival by Kaplan-Meier analysis." (PMID 29416729, 2018). "The infiltration of Foxp3+ T cells and CD33+ MDSC into the tumor nest was rare, thus we calculated the densities of these cells in total tumor area." (PMID 30285868, 2018). "The cut-off levels for high or low infiltration of the residual tumour after NAC were as follows: CD8+ TILs, 42; FOXP3+ TILs, 7 and CFR, 7.0." (PMID 30233820, 2018). "Another study focusing on epigenetic hallmarks of tTregs found that TI-Tregs had consistently hypomethylated Foxp3 CNS2 in various orthotopic and heterotopic transplanted tumor models, even at different time points of tumor growth." (PMID 29887862, 2018). "Using a full panel of immune cell markers (CD3, CD8, PD1, Foxp3, CD68 and CD163), we asked how similar different tumor types were in terms of immune cell spatial layout." (PMID 30179157, 2018). "We used immunohistochemistry to examine the subcellular localization and expression levels of HMGB1 and HMGN1, as well as tumor CD3+, CD8+, FOXP3+ lymphocyte infiltration, and the expression of immune inhibiting molecules PD-1/PD-L1." (PMID 30619746, 2018). "Neoadjuvant chemotherapy seemed to result in a relocation of Th1-committed CD4+ T cells from blood, presumably to the tumour, indicated by shifts in the methylation patterns, whereas no such shifts were seen for lineages corresponding to IL13, IL17A and FOXP3." (PMID 30075815, 2018). "High tumor grade correlated with higher frequencies of CD3+, CD68+ CD163+ TAMs, and CD25+ FOXP3+ Treg cells, but Treg frequencies were significant predictors of favorable prognosis in patients with familial ovarian cancer (11/73 patients with BRCA mutation)." (PMID 30042343, 2018).
tumor (continued). "We evaluated, by qRT‐PCR, 826 tumor tissue samples for mRNA expression of CD3, CD8, and FOXP3 for potential prognostic significance in terms of disease‐free survival (DFS) and overall survival (OS)." (PMID 30240146, 2018). "We detected the density and distribution of CD8+ T cells, CD4+ T cells, Foxp3+ T cells and CD33+ MDSC infiltrating the tumor site." (PMID 30285868, 2018). "When administrated to the B16F10 tumor-bearing mice, Roxyl-WL can inhibit IDO1 activity, suppress the tumor growth, reduce the number of Foxp3+ Tregs, and decrease the Kyn/Trp ratio evidently." (PMID 29932010, 2018). "After vaccination of B1610 tumor mice with PSPEI-PAA nanocomplex, single cell suspension of the isolated tumor and tumor draining lymph node were then prepared for the assessment of the matured DCs, CD8+, CD4+ and CD4+FOXP3+ T lymphocytes." (PMID 30960988, 2018). "The percentages of activated CD4+Foxp3− and CD8+IFN-γ+ T cells from tumours receiving vvDD-IL-2-RG treatment were increased, compared to those treated with other viruses." (PMID 30410056, 2018). "In contrast to the immunosuppressive effect of FOXP3 Treg cells, CD8 cytotoxic T cells are considered to be the major effector immune cells against tumor cells." (PMID 30153850, 2018). "At last, one tumor characteristic (TNM stage) and four immune variables (CD8, Foxp3, CD33, PD-L1-TC) had independent prognostic value for the OS of ESCC patients." (PMID 30285868, 2018). "Loss of CD11b expression or function promotes immune suppressive gene expression in macrophages in vitro and TAMs in vivo, increases FoxP3+ CD4+ T cells and decreases CD8+ T cell recruitment to tumors and increases tumor growth." (PMID 30568188, 2018). "Owning to the relationships and functions of CD8+ TILs, FoxP3+ Tregs and TGF-β in tumor tissues, we attempted to block both CD25 and TGF-β in mice models." (PMID 30359281, 2018). "Full data regarding distribution of CD8, FOXP3, CD8/FOXP3 ratio, and PD-L1 according to tumor subtype and other clinical variables is detailed in." (PMID 29929548, 2018). "Conversely, in preclinical studies, the presence of immunosuppressive CD4+CD25+FOXP3+ regulatory T cells and immunosuppressive soluble factors inside the tumor corresponded with poor prognosis in MPM, due to suppression of anti-tumor immune responses." (PMID 29342862, 2018). "After adjustment by TNM stage, four immune variables including the infiltration of CD8+/Foxp3+/CD33+ cells and the PD-L1 expression by tumor cells were selected to construct a prognostic nomogram." (PMID 30285868, 2018). "However, frequency of regulatory T cells (Treg, Foxp3+CD4+ T) was reduced in the tumor of Eomesfl/flCd4Cre mice, suggesting that Eomes might play a role in development or maintenance of intra-tumoral Treg cells instead of regulating effector functions of CD4+ T cells." (PMID 30619337, 2018). "Tumor-infiltrating CD8+ T cells are believed to be the front fighter against tumor, while Foxp3+ T cells can suppress the proliferation and activation of CD8+ T cells." (PMID 30474571, 2018). "Maximal tumour shrinkage coincided with a decreased Ki67 proliferative index, increases in tumour CD8+ cytotoxic T cells, FoxP3+ Tregs, and NK cells, as well as higher granzyme B staining and IFNγ production, confirming increased cytotoxicity." (PMID 30327563, 2018). "In addition, it is of interest to explore whether normal reference ranges of CD4+CD25+FOXP3+ Treg could be established according to different age groups, which may make it possible to evaluate immune-activity against a tumour through regular monitoring of Treg populations." (PMID 28253320, 2017). "To study the involvement of RUNX3 in FOXP3 transcription we transfected CD8+ T cells with control- or RUNX3-siRNA and then cultured these cells in in vitro tumor microenvironment." (PMID 28487507, 2017). "In the tumor microenvironment, PD-1 expressed on Tregs accelerates CD4+ T cells differentiating into Foxp3+ Tregs under the circumstances of CD3 and TGF-β." (PMID 27974689, 2017).